RBM39 (RNA binding motif protein 39)
Diseases named in the same sentence as RBM39 in open-access papers (continued):
Sharing a sentence is not in itself a finding about the gene and the disease.
tumor (continued). "After release from PGRMC1, FXR1 and RBM39 bind and stabilize progesterone receptor (PR) transcript to enable expression of PR protein, which induces cell cycle, membrane, and cytoskeleton remodeling genes that drive tumor growth." (PMID 42282014, 2026). "It provides critical insights into the complex regulatory network of RBM39 in tumor biology." (PMID 40302803, 2025). "This complicates determining whether the suppression of tumor cell migration, invasion, and stemness is solely due to RBM39 inhibition or is also influenced by the reduced proliferative capacity caused by Indisulam." (PMID 40465651, 2025). "In nude mice xenograft model, RBM39 knockdown significantly suppressed tumor formation." (PMID 40302803, 2025). "RBM39 in NK cells could possibly affect the anti-tumor functions of NK cells, which needs to be tested in future studies by using a conditional RBM39 knockout mouse." (PMID 40962798, 2025). "RBM39-mediated upregulation of aspartic acid synthesis leads to increased arginine uptake, forming a positive feedback loop to maintain high levels of arginine and tumor metabolism." (PMID 39612465, 2024). "In an mTOR-driven HCC mouse model, tumor cells also increased arginine import and reduced its conversion to polyamines, driving oncogenic metabolism via the arginine-binding factor RNA-binding motif protein 39 (RBM39)." (PMID 38297372, 2024). "Moreover, HE staining and immunohistochemical analyses of the mouse bone, liver, and spleen tissues revealed a noticeable reduction in tumor cell infiltration and decreased expression of Ki67 and RBM39." (PMID 39044280, 2024). "Moreover, the regulation of RBM39 by indisulam has been found to activate anti‐tumor immunity and enhance checkpoint immunotherapy." (PMID 38903537, 2024). "In mTOR-driven HCC models, tumor cells also enhance arginine uptake while reducing its conversion to polyamines, thus promoting oncogenic metabolism through the arginine-binding protein RNA binding motif protein 39 (RBM39)." (PMID 39610917, 2024). "Moreover, knockdown of Rbm39 correlated with decreased Asns mRNA and arginine levels in non-tumor tissue, supporting the notion that RBM39 transcriptionally controls ASNS, which in turn promotes arginine uptake." (PMID 37804830, 2023). "On day 4, xenograft tumour volume was still similar to starting volume (indisulam arm n = 5, 94% ± 48%), and immunofluorescence of xenograft tumours (n = 2 vehicle, n = 2 indisulam) revealed a reduction of RBM39 in the presence of proliferation marker Ki67 i.e. in context of viable tumour." (PMID 35296644, 2022). "Until recently the key molecular event determining the anti-tumour activity of aryl sulfonamides, selective RBM39 degradation, was unknown and predictive biomarkers for therapy response unavailable." (PMID 35296644, 2022). "This might imply that RBM39 expression levels influence tumour TMB and MSI, and consequently the patient's response to immune checkpoint inhibition medication." (PMID 35989423, 2022). "Our results suggest that RBM39 may play an important role in tumours and serve as a prognostic factor." (PMID 35989423, 2022). "Next, we investigated how RBM39 expression differed by age in patients with different tumour types." (PMID 35989423, 2022). "RBM39 was positively or negatively correlated with the prognosis of different tumours." (PMID 35989423, 2022). "We analysed the relationship between RBM39 expression and the number of neoantigens in 19 tumours." (PMID 35989423, 2022). "Therefore, the current tumor-targeted RNA splicing of indisulam is to recruit DCAF15 to induce the degradation of mRNA splicing factor RBM39 to target splicing." (PMID 34389703, 2021). "Although the role of other members of the RBM proteins family in tumor treatment and prognosis is not clear, existing studies have shown that some members of RBM proteins family, such as RBM3, RBM4, and RBM39, play an essential role in tumor treatment and prognostic markers." (PMID 34804951, 2021).
tumor (continued). "Moreover, the research offers an experimental platform for the development of small molecule inhibitors of RBM39, such as aryl sulfonamides like indisulam, or RNA interference drugs, paving the way for the discovery of novel anti-tumor medications targeting RBM39." (PMID 40302803, 2025). "Interestingly, RBM39 is a potential tumor suppressor in few human malignancies." (PMID 34389703, 2021). "To evaluate the potential of indisulam to inhibit tumor growth in HNSCC, we first investigated the expression levels of RBM39, a critical target of indisulam, and its relationship with the splicing burden in patient samples." (PMID 40227602, 2025). "USP39’s role in gastric cancer, which involves regulating tumor progression through interactions with PARP, RBM39, and miR-133a, emphasizes its potential as a promising clinical target for therapeutic applications." (PMID 40672756, 2025). "Given the critical role of RBM39 in tumorigenesis, a small molecule (indisulam) that targets and degrades RBM39 has been found to be an effective treatment for HCC and other tumor types." (PMID 39920310, 2025). "Immunoblotting of tissues clearly indicated the high expression of RBM39 and USP39 in tumor tissues and their protein levels also had a positive correlation with a Pearson’s correlation coefficient of 0.45." (PMID 39260689, 2024). "Although RBM5, RBM17, and RBM39 belong to the RNA-binding motif (RBM) family protein, their regulatory role in tumor progression is largely variable." (PMID 38216972, 2024). "By constructing in vivo and in vitro models with RBM39 interference, we found that RBM39 is crucial for the proliferation and survival of T-ALL tumor cells." (PMID 39044280, 2024). "Recently, indisulam has been proved as a natural molecular glue that binds to RNA binding motif protein 39 (RBM39) and regulates alternative splicing to exert anti-tumor effects." (PMID 38593113, 2024). "For example, RBM39 positively correlates with aDC in LIHC, while it negatively correlates with aDC in the other seven tumours." (PMID 35989423, 2022). "We also looked at the sensitivity of tumor cells with WT KRAS to treatment with Indisulam, and demonstrated that KRAS4A was downregulated in response to both Indisulam and knockdown of RBM39 in H1650 cells." (PMID 34257283, 2021). "Compared with Indisulam treatment alone, the combination of RBM39-KO and Indisulam did not significantly enhance the suppression of tumor stemness, proliferation, migration, or invasion, further supporting the role of RBM39 as the target protein of Indisulam." (PMID 40465651, 2025). "The results indicate that although PRMT6-mediated RBM39 methylation promoted the growth and metastasis of NSCLC cells, PRMT6 may also play a pro-tumor role through other target proteins when RBM39 is knocked out." (PMID 40465651, 2025). "Rbm39 knockdown reduced tumor burden in L-dKO mice, and as observed upon ARG1 or AGMAT overexpression and Asns knockdown, Rbm39 knockdown was detected only in non-tumor tissue." (PMID 37804830, 2023). "Although DCAF15 is a strong determinant for indisulam sensitivity as shown by us and others, a recent study suggested that DCAF15 mRNA levels in primary samples of tumour cells of AML patients did not correlate to RBM39 degradation." (PMID 35296644, 2022). "In addition, RBM39 knockdown by siRNA induced alternative splicing and suppressed proliferation, which indicates that the tumor suppressive effect of indisulam depends on RBM39, not by targeting other molecules." (PMID 39004623, 2024). "For retained introns (RI), the deletion of TSSC4 resulted in a significant decrease in the IncLevels of several tumor-regulatory genes, such as ITGA3 (decreased by 0.284), RBM39 (decreased by 0.164) and NONO (decreased by 0.125)." (PMID 39697342, 2024).
infection (6 papers, 2012 to 2025). The state of being infected such as from the introduction of a foreign agent such as serum, vaccine, antigenic substance or organism. "After collecting cells and extracting total RNA at different time points (12 h, 24 h and 36 h) post-infection, mRNA abundance of RBM39 was analyzed by quantitative reverse transcription-PCR (qRT-PCR)." (PMID 34079549, 2021). "To provide comprehensive data and reliable evidence for the promotion role of RBM39 in CSC-like properties and EMT, we overexpressed RBM39 in H460 and A549 cells by lentiviral infection." (PMID 40465651, 2025). "To verify the expression level of RBM39 after infection with other RNA viruses, we infected cells with SeV and VSV, and then extracted the total RNA of the cells at 0, 6, 12 and 24 h after infection, and analyzed the mRNA level of RBM39 by qRT-PCR." (PMID 34079549, 2021). "Interestingly, however, in DENV2 infection, we determined small but significantly different changes in exon inclusion/exclusion levels in CHID1, SRSF2, HNRNPDL, and RBM39." (PMID 32380717, 2020).
bacterial infection (1 paper, 2023). "Finally, LDLRAD1 is known to be potentially involved in resistance against bacterial infection, while RBM39 has been proposed as target of putative selective sweep in swine being involved in RNA splicing and RNA processing." (PMID 37605116, 2023).
degenerative diseases (1 paper, 2025). "RBM39 is mainly involved in RNA splicing, and its dysfunction can lead to degenerative diseases." (PMID 40943121, 2025).
neurological diseases (1 paper, 2020). "HNRNPDL and RBM39 function in transcriptional regulation, HNRNPDL and SRSF2 regulate alternative splicing, MPRIP is involved in stress granule formation, CHID1 has a role in pathogen sensing, and KIF21A has been implicated in neurological diseases." (PMID 32380717, 2020).
RBM39 also shares sentences with these, for which no sentence is quoted: kidney clear cell carcinoma (2 papers); lymphoid cancers (2); rectum adenocarcinoma (2); sarcoma (2); adenocarcinoma (1); adenoid cystic carcinoma (1); adenoma (1); anorexia nervosa (1); autism spectrum disorder (1); bulimia nervosa (1); chronic myelomonocytic leukemia (1); colorectal adenoma (1); endometrial cancer (1); epilepsy (1); head and neck squamous cell carcinoma (1); Hepatic fibrosis (1); hepatitis B (1); hepatitis C (1); hereditary leiomyomatosis (1); lipoid proteinosis (1); lung squamous cell carcinoma (1); neuroendocrine neoplasm (1); non-small cell lung carcinoma (1); Oral Cancer (1); pharyngeal cancer (1); pheochromocytoma (1); T-cell acute leukemia (1); type 2 diabetes (1); uterine carcinoma (1).